GABRQ (gamma-aminobutyric acid type A receptor subunit theta)
Description:
Theta subunit of the heteropentameric ligand-gated chloride channel gated by gamma-aminobutyric acid (GABA), a major inhibitory neurotransmitter in the brain. GABA-gated chloride channels, also named GABA(A) receptors (GABAAR), consist of five subunits arranged around a central pore and contain GABA active binding site(s) located at the alpha and beta subunit interfaces (By similarity). When activated by GABA, GABAARs selectively allow the flow of chloride anions across the cell membrane down their electrochemical gradient.
Synonyms: THETA
Tractability: Small molecule: an approved drug acts on it; a high-quality ligand is known; it belongs to a druggable protein family. Antibody: its Gene Ontology location is reachable by antibodies, with high confidence; UniProt places it where antibodies can reach, with medium confidence; UniProt predicts a signal peptide or a membrane-spanning region. PROTAC: a small molecule that binds it is known.
Gene: Protein-coding gene on chromosome X (152,637,895 to 152,657,542, forward strand). Ensembl gene ENSG00000268089.
Subcellular location: Postsynaptic cell membrane; Cell membrane
Pathways (Reactome):
Neuronal System: GABA receptor activation
Signal Transduction: Signaling by ERBB4
Gene Ontology:
Molecular function: GABA-A receptor activity; GABA-gated chloride ion channel activity; protein binding; neurotransmitter transmembrane transporter activity; transmembrane signaling receptor activity; extracellular ligand-gated monoatomic ion channel activity; monoatomic ion channel activity
Biological process: chloride transmembrane transport; gamma-aminobutyric acid signaling pathway; signal transduction; synaptic transmission, GABAergic; monoatomic ion transmembrane transport; monoatomic ion transport; neurotransmitter transport
Cellular component: receptor complex; GABA-A receptor complex; GABA-ergic synapse; plasma membrane; membrane; postsynaptic membrane
Homologues: Orthologues: chimpanzee GABRQ (99% identical), macaque GABRQ (97% identical), mouse Gabrq (78% identical), rat Gabrq (77% identical), pig GABRQ (70% identical), rabbit GABRQ (70% identical), guinea pig GABRQ (59% identical). Paralogues in human: GABRB1 (33% identical), GABRB3 (32% identical), GABRB2 (31% identical), GABRD (26% identical), GLRA2 (25% identical), GLRA3 (25% identical), GLRA1 (24% identical), GABRP (24% identical), GABRR2 (23% identical), GABRR3 (23% identical), GLRB (23% identical), GABRA4 (23% identical), and 33 more.
Diseases named in the same sentence as GABRQ in open-access papers:
GABRQ is named in the same sentence as 22 diseases in open-access papers, as found by Europe PMC text mining. Sharing a sentence is not in itself a finding about the gene and the disease. The quoted sentences say what the papers report.
frontotemporal dementia (5 papers, 2020 to 2024). Frontotemporal dementia (FTD) comprises a group of neurodegenerative disorders, characterized by progressive changes in behavior, executive dysfunction and language impairment, as a result of degeneration of the medial prefrontal and frontoinsular cortices. "The loss of von Economo neurons (VENs) and GABA receptor subunit theta (GABRQ) containing neurons is linked to early changes in social–emotional cognition and is seen in frontotemporal dementia (FTD) due to C9orf72 repeat expansion." (PMID 35152451, 2022). "Additionally, anterior hippocampus gene GABRQ was also highly expressed in regions both structurally covarying with the anterior hippocampus and those vulnerable to frontotemporal dementia." (PMID 32075960, 2020).
Alzheimer disease (4 papers, 2019 to 2024). A progressive, neurodegenerative disease characterized by loss of function and death of nerve cells in several areas of the brain leading to loss of cognitive function such as memory and language. "We quantified VENs and GABRQ‐immunopositive neurons in the anterior cingulate cortex (ACC) in FTD with underlying TDP43 (FTLD‐TDP) (n = 34), tau (FTLD‐tau) (n = 24) or FUS (FTLD‐FUS) (n = 8) pathology, neurologically healthy controls (n = 12) and Alzheimer's disease (AD) (n = 7)." (PMID 35152451, 2022). "We quantified VENs and GABRQ immunopositive neurons in the anterior cingulate cortex (ACC) in C9‐bvFTD (n = 16), controls (n = 12) and Alzheimer's disease (AD) (n = 7)." (PMID 31066065, 2019).
hepatocellular carcinoma (4 papers, 2013 to 2022). A malignant tumor that arises from hepatocytes. "The GABRQ is overexpressed in hepatocellular carcinoma cells but not in a normal cell line and GABA in the liver promotes the proliferation of cancer cells through GABRQ." (PMID 26491438, 2015).
migraine (4 papers, 2008 to 2024). "Another GABRQ coding variant, rs3810651, is a missense polymorphism in the last exon of GABRQ and was explored for association with neurological disorders like migraine, essential tremor and restless leg syndrome." (PMID 33772085, 2021). "We analyzed the distribution of allelic, genotypic and haplotypic frequencies of twenty-three SNPs localized in the GABRE, GABRA3 and GABRQ genes to explore the role of these genes in migraine susceptibility using a case-control approach." (PMID 24040174, 2013). "The AT genotype of rs3810651 of GABRQ gene showed an increased risk for migraine (OR: 4.07; 95% CI: 1.71-9.73, p=0.002), still significant after Bonferroni correction." (PMID 24040174, 2013). "Three markers located within 15 kb of the coding region of the GABRE gene and a marker in the GABRQ gene were analyzed for association with migraine in a large population (275 migraineurs versus 275 healthy individuals) of Australia Caucasians." (PMID 19087248, 2008). "Regarding the genotypic analyses a set of interesting results reinforced the role of two genes (GABRA3 and GABRQ) in migraine." (PMID 24040174, 2013). "In this study, we have focused on the subunit GABA A receptors type ε (GABRE) and type θ (GABRQ) genes and their involvement in migraine." (PMID 19087248, 2008). "Prior linkage studies have reported mapping of a migraine gene to chromosome Xq 24–28, a region containing a cluster of genes for GABA A receptors (GABRE, GABRA3, GABRQ), which are potential candidate genes for migraine." (PMID 19087248, 2008). "Distribution of the GABRQ gene exon 9 variation (P437I) in migraineurs and controls of original sample (MO migraine without aura, MA migraine with aura)." (PMID 19087248, 2008).
breast carcinoma (2 papers, 2023 to 2025). "We found that the seven GABAA receptor subunits were upregulated in TNBC breast cancers, including GABRA1, GABRA5, GABRD, GABRE, GABRP, GABRQ, and GABRG3." (PMID 36923530, 2023).
dementia (2 papers, 2019 to 2023). Loss of intellectual abilities interfering with an individual's social and occupational functions. "This indicates that the loss and sparing of these neuronal types in dementia occurs concurrently, and supports the hypothesis that VENs and GABRQ‐expressing neurons are related and together form a larger cortical population." (PMID 31066065, 2019).
essential tremor (2 papers, 2021 to 2024). A relatively common disorder characterized by a fairly specific pattern of tremors which are most prominent in the upper extremities and neck, inducing titubations of the head. "MC-106-4 and MC-170-3 have variants in GABRQ, associated with essential tremor and ASD40,41." (PMID 39632905, 2024).
autism (1 paper, 2021). Persistent deficits in social interaction and communication and interaction as well as a markedly restricted repertoire of activity and interest as well as repetitive patterns of behavior. "Analysis of association between GABRQ rs3810651 and ASD using diagnostic criteria mentioned in the DSM-5 and scores obtained through other ASD assessment tools like Autism Diagnostic Observation Schedule along with the Autism Diagnostic Interview-Revised may aid in strengthening our findings." (PMID 33772085, 2021).
clear cell renal cell carcinoma (1 paper, 2021). "γ-Aminobutyric acid (GABA) A receptor subunit θ (GABRQ) is a well-known inhibitory neurotransmitter in the brain, suggested as a prognostic biomarker of clear cell renal cell carcinoma (ccRCC)." (PMID 33450964, 2021).
liver cancer (1 paper, 2021). An epithelial or non-epithelial malignant neoplasm that arises from the liver. "A previous study reported that GABRQ is involved in the risk and progression of liver cancer, which promotes the proliferation of cancer cells." (PMID 33450964, 2021).
motor neuron disease (1 paper, 2019). "C9‐bvFTD donors that did not present with motor neuron disease (MND) symptoms in the first half of their disease course showed a prominent loss of GABRQ‐expressing neurons compared to controls." (PMID 31066065, 2019).
cancer (5 papers, 2015 to 2022). A tumor composed of atypical neoplastic, often pleomorphic cells that invade other tissues. "Expression of GABRG3, GABRQ, GABRE, and GABRR2 is correlated with inhibition of growth phenotypes in cell lines and with favorable patient outcomes (Broad Institute of MIT & Harvard, firebrowse.org), while expression of other transcripts (GABRB2, GABRP) is associated with cancer progression." (PMID 33187258, 2020). "Results showed that GABRA3, SLC6A3, GABRQ, SCN4A, and GABRG3 were overexpressed in cancer compared with normal liver tissues." (PMID 35401884, 2022). "Therefore, based on these results, we suggested that GABRA3, SLC6A3, GABRQ, and SCN4A might be cancer-specific targets of Carvacrol which were further screened in the subsequent study." (PMID 35401884, 2022). "Results showed that expressions of DRD1, GABRA3, SLC6A3, GABRQ, and SCN4A in cancer were significantly higher than those in noncancer tissues." (PMID 35401884, 2022).
infection (2 papers, 2016 to 2022). The state of being infected such as from the introduction of a foreign agent such as serum, vaccine, antigenic substance or organism. "Furthermore, we found that GABRD, GABRB3, GABRE, and GABRQ, which play important roles in neuron cell growth and migration, are significantly downregulated after infection." (PMID 36147849, 2022).
tumor (1 paper, 2021). "An important issue was to determine if genes other than GABRA3 and GABRQ, and in particular tumor suppressor genes, rely on a similar process of DNA hypomethylation-induced overlapping transcription to become hypermethylated in tumors." (PMID 34462486, 2021). "While studying the human MAGEA6/GABRA3 gene locus, we observed that DNA hypomethylation in tumor cells can lead to the activation of a long transcript (CT-GABRA3) that overlaps downstream promoters (GABRQ and GABRA3) and triggers their hypermethylation." (PMID 34462486, 2021). "Lack of GABRQ/GABRA3 and PTPRO/RERG promoter hypermethylation was indeed observed in a fraction of tumor samples that nevertheless produced the overlapping transcripts." (PMID 34462486, 2021).
GABRQ also shares sentences with these, for which no sentence is quoted: cervical cancer (1 paper); depression (1); mental disorder (1); neurological disorders (1); ovary cancer (1); Parkinson disease (1); psychosis (1); schizophrenia (1).